C3 (complement C3)
Diseases named in the same sentence as C3 in open-access papers (continued):
Sharing a sentence is not in itself a finding about the gene and the disease.
pneumonia (16 papers, 2012 to 2024). An acute, acute and chronic, or chronic inflammation focally or diffusely affecting the lung parenchyma, caused by an infection in one or both of the lungs (by bacteria, viruses, fungi, or mycoplasma.). "Primary C3 deficiencies, while rare, are associated with increased susceptibility to bacterial infections that primarily manifest in early childhood, marked by pneumonia and meningitis." (PMID 31301278, 2019). "By contrast, our patient presented mainly with pneumonias, and similar to other C3-deficient patients, he showed high levels of CRP and had episodes of fever, with infectious episodes persisting throughout adolescence." (PMID 22996269, 2013). "C3 was found to play a dominant role in pathogen-specific T-cell and B-cell responses, contributing to the amelioration of Chlamydia psittaci-induced pneumonia in mice." (PMID 38166725, 2024). "In this study, NAC combined therapy improved the immune function of pediatric pneumonia patients by elevating IgA, IgG, IgM, and C3." (PMID 39208656, 2024). "In contrast, patients with pneumonia had a greater incidence of C3 abnormalities, either elevated or reduced." (PMID 38585537, 2023). "In order to elucidate how much C3 is required to achieve full protection against C.ps., the course of induced pneumonia in terms of body weight and clinical score was not only investigated in homozygous C3+/+ (WT) and C3−/−, but also in heterozygous C3+/− mice." (PMID 33767691, 2021). "Nevertheless, the slow recovery of physiologic levels of complement C3/C4 under current management strategies might explain this increased incidence of pneumonia or hemorrhage." (PMID 23091606, 2012). "In addition, complement C3 depletion was correlated with increased odds of pneumonia and hemorrhage." (PMID 23091606, 2012). "Surprisingly, our data prove that for C. psittaci-induced pneumonia in mice, non-myeloid-derived, circulating/systemic C3 has a leading role in protection, in particular on the development of pathogen-specific T- and B- cell responses." (PMID 33746963, 2021). "Except of two patients who died from pneumonia, other non-survivors suffered from severe complement C3 depletion after admission." (PMID 23091606, 2012).
alopecia (15 papers, 2019 to 2026). Hair loss usually from the scalp. "Other research reports have also found that there is lymphocyte infiltration and complement C3 and immunoglobulin deposition around the hair follicles in the alopecia area, indicating that alopecia is related to the inflammatory immune response." (PMID 40075965, 2025). "Associated with several clinical manifestations, including Raynaud’s phenomenon, alopecia and leucopenia.Positively correlated with ANA and anti-dsDNA levels.Negatively associated with absolute neutrophil count and C3." (PMID 39835138, 2024). "Furthermore, presence of the anti-dsDNA antibody was related to more serious kidney injury, lower levels of complement C3, fever, alopecia, PAH and less prevalence of ILD." (PMID 37344560, 2023). "Regarding the clinical items included in the classification criteria, acute cutaneous lupus and nonscarring alopecia manifestations were significantly more prevalent in patients with SLE with low C3 and low C4 levels." (PMID 41458496, 2025). "For this, the differential influence of anti-Smith antibodies (ADS) (p < 0.004) and low C3/C4 (p < 0.03) statistically favored clinical SLE+ determinations, while proteinuria (p < 0.009) and non-scarring alopecia (NSA) (p < 0.015) had elevated representation in UCTD determinations." (PMID 41008780, 2025).
coronary artery disease (15 papers, 2010 to 2025). "Early work has shown an association between C3 plasma levels and coronary artery disease." (PMID 34830419, 2021). "Increased C3 levels have been reported as a prognostic marker of future cardiovascular events in both men and women and were associated with an increased risk for coronary heart disease." (PMID 31193778, 2019). "have found plasma C3 levels significantly higher than fasting at 2, 4, and 6 hours after fat ingestion (50g/m2 of fat) by normolipidemic subjects with coronary artery disease and healthy controls." (PMID 27901186, 2017). "Similarly, in a study involving a cohort of 756 unselected adults, a notable odds ratio for the likelihood of coronary heart disease was identified based on C3 serum levels." (PMID 39072319, 2024). "However, links with vascular disease are less convincing; the Arg102Gly polymorphism has shown associations with C3 plasma levels, but not with the presence or severity of coronary artery disease, casting doubts on the importance of this polymorphism in vascular pathology." (PMID 34830419, 2021).
gastric cancer (15 papers, 2008 to 2025). A primary or metastatic malignant neoplasm involving the stomach. "Complement C3 depletion occurring in gastric cancer was associated with poor short-term and long-term outcomes." (PMID 29062836, 2017). "The combined use of arginine and glutamine in enteral and parenteral nutrition for patients after gastric cancer surgery has led to increased levels of albumin, serum protein, and transferrin, as well as decreased levels of C-reactive protein, C3, and C4." (PMID 39897929, 2025). "High C3 deposition was identified as an independent prognostic factor of poor 5-year overall survival, suggesting that local C3 deposition in the tumor microenvironment is a relevant immune signature for predicting prognosis of gastric cancer." (PMID 33193442, 2020). "Among the hits identified in the CagA screen, 4 of them (MMP1, CEACAM6, ITGA2, C3) showed at least 2-fold increases in gastric cancer when compared to normal controls." (PMID 27421133, 2016). "Local C3 deposition has been suggested as a prognostic factor for gastric cancer." (PMID 40698088, 2025). "Interestingly, increased C3 expression was shown to trigger the JAK/STAT3 pathway in gastric cancer, which led to a subsequent increase in cell proliferation." (PMID 40698088, 2025). "In summary, our results demonstrate that complement C3 depletion could indicate poor clinical outcomes for gastric cancer patients in China." (PMID 29062836, 2017). "Activation of the complement protein C3 in human gastric cancer (GC) is characterized by the localized buildup of C3 and its effectors, as well as a decrease in plasma C3 levels, which appears to contribute to tumour progression and poor prognosis in patients with GC." (PMID 38902713, 2024). "Correlation of C3, CR4, and C5aR1 expression and clinical prognosis in gastric cancer with different clinicopathological factors via Kaplan-Meier plotter." (PMID 33614473, 2020). "Lysophosphatidic acid-induced cell invasion and migration were significantly inhibited using either NET1 siRNA or a RhoA inhibitor (C3 exoenzyme), thus indicating the activity of both NET1 and RhoA in gastric cancer progression." (PMID 18827818, 2008). "Overexpressed C3 could activate JAK2/STAT3 pathway, which has a correlation with the progression of gastric cancer." (PMID 40396123, 2025).
monoclonal gammopathy (15 papers, 2017 to 2025). A condition characterized by the abnormal presence of monoclonal immunoglobulins in the blood or urine. "Additional workup confirmed elevated serum creatinine, albuminuria (2.9 g/d), and hematuria 3+ with persistent monoclonal gammopathy (IgGκ); the patient’s C3 serum level was normal." (PMID 39810761, 2025). "Laboratory predictors include hypocomplementemia (particularly low C4 and C3), cryoglobulinemia, cytopenias, monoclonal gammopathy, and elevated beta-2-microglobulin." (PMID 41531558, 2025). "A repeat biopsy of the abdominal skin in February 2025 revealed elastolytic giant cell granulomas with co-deposition of IgG1, lambda light chain, C3, C4, and C1q, indicating monoclonal gammopathy of dermatologic significance." (PMID 41403934, 2025). "Herein, we report the first FNG case with strong IgA and C3 immunostaining in renal biopsy concurrent with monoclonal gammopathy (MG)." (PMID 36451151, 2022). "Herein, we report a case of fibronectin glomerulopathy presenting as strong IgA and C3 immunostaining in renal biopsy, concomitant with monoclonal gammopathy (monoclonal IgA κ)." (PMID 36451151, 2022). "Prognostic markers that are associated with severe extra-glandular disease include hypocomplementia (C3 and C4), cryoglobulinemia, monoclonal gammopathy, anti-Ro, anti-La, RF, and hypergammaglobulinemia, most of which were also present in our patient." (PMID 36253840, 2022). "mIg-C3G was diagnosed in 2 patients aged 75 and 77 years who had indolent multiple myeloma or monoclonal gammopathy of undetermined significance (MGUS), including one with low serum level of C3 (sC3, 0.66 g/L)." (PMID 39554253, 2024). "Patients with cytopenias had a high risk of non-MALT B-cell and non-B-cell cancer, while those with low C3 levels had a high risk of MALT lymphomas and those with monoclonal gammopathy and low C4 levels had a high risk of non-MALT lymphomas." (PMID 28416003, 2017).
anaphylaxis (14 papers, 2016 to 2025). An acute hypersensitivity reaction that occurs from exposure to an allergen. "Increased amounts of C3 protein were shown to provoke mast cell activation, and various mast cell mediators were implicated in the regulation of coagulation and fibrinolysis in anaphylaxis." (PMID 40698088, 2025).
Cerebral ischemia (14 papers, 2009 to 2024). Restriction of arterial blood supply to the brain associated with insufficient oxygenation to support the metabolic requirements of the tissue. "It has been also shown that C3 regulates hippocampal neurogenesis in adult mammalian brain and C3-deficient mice present impaired neurogenesis following cerebral ischemia." (PMID 27769255, 2016). "Furthermore, inhibition or deficiency in complement C3 showed neuroprotective effects in a cerebral ischemia model." (PMID 37268807, 2023). "Also, it has been shown that C3 regulates hippocampal neurogenesis in adult mammalian brain and C3-deficient mice present impaired neurogenesis following cerebral ischemia." (PMID 25617152, 2015). "On the other hand, some complement proteins, such as C1q and C3, are pathologically increased in the CSF of patients with MS, where elevated C3 levels correlate significantly with disease progression, and in cerebral ischemia." (PMID 39022733, 2024). "As KLF4 is a key factor in regulating inflammation, it seems likely that the enhanced KLF4 suppresses the astrocytic expression of C3 after cerebral ischemia." (PMID 36823628, 2023). "The neuronal overproduction of the β-amyloid peptide, after cerebral ischemia, stimulates astrocytes to release complement C3, which binds to C3a receptors on neurons and microglia and causes impaired phagocytosis of microglia." (PMID 32501292, 2020). "In a mouse model of transient MCAO, inhibiting C3 activity via genetic knockout or antioxidant N-tert-butyl-α-phenylnitrone treatment could alleviate inflammatory response, reduce brain infarct volume, and attenuate neurological deficiency following 1 to 7 days of brain ischemia." (PMID 31011487, 2019). "Evidence for C3 cleavage after brain ischemia was obtained by studying frozen brain tissue that was homogenized with detergent and examined by Western blotting using development with anti-C3 antibody." (PMID 20140243, 2010). "Therefore, C3 activity should be modulated rather than indiscriminately eliminated, such as with genetic knock-out or depletion with CVF, to attenuate C3-mediated injury after cerebral ischemia." (PMID 31011487, 2019). "Selective complement inhibition, particularly of C3, is therefore an attractive strategy for global cerebral ischemia-reperfusion injury following OHCA, and may thereby improve long-term outcomes." (PMID 20150958, 2009).
end-stage renal disease (14 papers, 2014 to 2024). "The R161W variant in C3 causes hyperactive C3 convertase activity; this change increased the binding of C3b to factor B and reduced the binding of C3b to CFH and MCP, and resulted in a rapid progression to end stage renal failure." (PMID 25188723, 2014).
epilepsy (14 papers, 2010 to 2025). A brain disorder characterized by episodes of abnormally increased neuronal discharge resulting in transient episodes of sensory or motor neurological dysfunction, or psychic dysfunction. "First, due to the lack of detailed clinical information (e.g., etiological subtypes of TLE), we were unable to determine whether distinct epilepsy syndromes are associated with differential C3 expression levels." (PMID 41346378, 2025). "Interestingly, in our study, C3-deficient mice had slightly milder seizure scores, which was consistent with other studies indicating the pathogenic role of C3 in epilepsy." (PMID 39456256, 2024). "Inter-individual variations of C3 expression during brain development would then influence the building of neuronal circuits and the labeling of imprecise connections, hence favoring future susceptibility to seizures and epilepsy." (PMID 20862287, 2010). "We previously reported that complement C3 is elevated in brain biopsies from human drug-resistant epilepsy and in experimental rodent models." (PMID 38035266, 2023). "Our results found that C3 expression is reduced in the interaction between epilepsy and stress cardiomyopathy." (PMID 36776884, 2023). "While contemporary findings indicate that increases in C3 complement activation occur in seizure disorders [reviewed in Wyatt-Johnson and Brewster (2020)], the specific pathophysiological consequences in epilepsy remain to be elucidated." (PMID 38035266, 2023). "The complement system is linked to a range of neurological diseases, including in neonates and in epilepsy, and changes in C3 have, for example, been used as an indicator of astrocyte polarisation in response to treatment in a rat epilepsy model." (PMID 37511288, 2023). "The similar effect of C3aRA and PKM2 siRNA-LPS-MCM-ACM on reducing C3–C3aR interaction verified the role of microglia PKM2 on the C3/C3aR pathway in neuroinflammation in epilepsy." (PMID 36831807, 2023). "Recent studies also prove that RNA transcripts and protein levels of C1q and C3 are increased in the hippocampus of patients and animal models of epilepsy." (PMID 36104755, 2022). "Mechanistically, continuous captopril therapy inhibited glial activation and aberrant synaptic phagocytosis in the hippocampus by reducing complement C3–C3ar expression in epilepsy." (PMID 36104755, 2022). "Conversely, a follow-up study surprisingly revealed that complement component factor H (CFH), a specific inhibitor of the C3 to C3b transition, was downregulated in rat hippocampal tissue after epilepsy induced by electrical stimulation." (PMID 33925147, 2021). "The concentration of serum C3 in untreated patients with epilepsy were shown to be significantly higher than in that of healthy controls." (PMID 31312171, 2019). "There is growing evidence for an important role of the complement system in CNS development and functioning and for the involvement of the complement system and particularly of C3 dysregulation, in the epilepsies – including the MTLE." (PMID 20862287, 2010). "High levels of complement molecules, including C3, are consistently found in brain biopsies derived from patients with different epilepsies with drug-resistant seizures such as focal cortical dysplasia (FCD), tuberous sclerosis complex (TSC), and temporal lobe epilepsy (TLE)." (PMID 38035266, 2023). "Captopril's effects on epilepsy-related glial activation, neuroinflammation, synaptic pruning, epileptogenesis, and cognitive dysfunction were at least partially reversed by administration of the effective C3 cleaved product, C3a." (PMID 36104755, 2022). "Furthermore, when C3a, an active cleavage product of C3, was administered intranasally, we found the beneficial effects of captopril on the prevention of epilepsy and its related complications were partially blocked." (PMID 36104755, 2022).
epilepsy (continued). "Investigation into the plasma concentrations of a panel of complement analytes in epileptic subjects presented a highly predictive model comprising of 6 complement analytes (C3, C4, properdin, FH, C1Inh, and Clu) which distinguish between epilepsy cases and controls." (PMID 31312171, 2019). "Genetic associations of several complement genes including its central component C3 with disorders of the central nervous system, and the existence of C3 dysregulation in the epilepsies and in the MTLE particularly, make it the C3 gene a good candidate for human MTLE." (PMID 20862287, 2010). "In addition, complement C3 is characteristic of neurotoxic “A1” astrocytes and its production in astrocytes is upregulated in aging and in disease and in experimental epilepsy." (PMID 38035266, 2023). "In epilepsy, high levels of C1q, C3, and TREM2/DAP12 receptor have been found in hippocampal samples from different forms of human and animal models of epilepsy, suggesting an abnormal phagocytosis of synapses and/or neurons." (PMID 32521797, 2020). "The 5 Hub genes, including C3, CD44, ANXA2, HTR1E, and APP, were also identified as the BottleNeck genes, that is, they are Hub-BottleNeck genes, indicating that they are much more important than the remaining Hub genes in the pathogenesis of epilepsy in PT." (PMID 33123575, 2020).
Hypoalbuminemia (14 papers, 2016 to 2025). The concentration of albumin in the blood circulation is below the lower limit of normal. "Laboratory investigations showed hypoalbuminemia, elevated D-dimer and fibrin degradation products, decreased IgG, IgM, and C3, and a positive antinuclear antibody at 1:100 coarse speckled pattern." (PMID 41398802, 2025). "Laboratory investigations revealed hypoalbuminemia, elevated D-dimer and fibrin degradation products, decreased IgG, IgM, and C3 levels, and a positive antinuclear antibody at a titer of 1:100 with a coarse speckled pattern." (PMID 41398802, 2025). "Additionally, hypoalbuminemia induced hepatic resynthesis of protein, resulting in elevated levels of cholesterol, C3 and C4." (PMID 38699483, 2024). "Laboratory tests revealed hypoalbuminemia, increased serum creatinine and low serum C3 level." (PMID 37226096, 2023). "The association remains robust after adjusted by age, sex and clinical indicators (SBP, eGFR, blood urea nitrogen, hypoalbuminemia, uric acid, serum triglycerides, hemoglobin, serum C3, urine protein, Oxford Classification T and glucocorticoid treatment) (HR = 2.21, 95%CI 1.35-3.62)." (PMID 29088730, 2017). "Indeed, despite comparable anti-THSD7A titers, C3−/− mice, which showed an interruption of the complement cascade at the level of C3, developed lower overall proteinuria, less hypoalbuminemia, less hyperlipidemia, and less pronounced podocyte foot process effacement than WT littermate controls." (PMID 36709213, 2023).
Allergy (13 papers, 2013 to 2024). An allergy is an immune response or reaction to substances that are usually not harmful. "Potentially more downstream of the effects of C3 and chemokines are the other strongly DE genes that were upregulated in S + C swine and associated with allergy—the mucin MUC5AC, and the serum amyloid A 3 (SAA3)." (PMID 36452260, 2022). "The role of the C3,C4 and C5 complement components and its anaphylatoxins C3a, C4a, and C5a in the development and promotion of allergies are widely discussed in the literature." (PMID 35504938, 2022).